ITGB3 (integrin subunit beta 3)
Diseases named in the same sentence as ITGB3 in open-access papers (continued):
Sharing a sentence is not in itself a finding about the gene and the disease.
ITGB3 also shares sentences with these, for which no sentence is quoted: ischemic stroke (9 papers); thrombosis (7); coronary artery disease (5); immune thrombocytopenia (5); dyslipidemia (3); heart failure (3); hepatocellular carcinoma (3); acute megakaryoblastic leukemia (2); acute respiratory distress syndrome (2); adenocarcinoma (2); allergies (2); cardiomyopathy (2); Disseminated intravascular coagulation (2); glaucoma (2); lymphogranulomatosis (2); lymphoma (2); neuroblastoma (2); Obesity (2); platelet disorder (2); steatosis (2); thrombophilia (2); type 2 diabetes (2); acute myocardial infarction (1); anaphylaxis (1); anemia (1); aspiration pneumonia (1); astrocytoma (1); attention deficit-hyperactivity disorder (1); Autoimmunity (1); bacterial endocarditis (1).
A further 99 diseases each share a sentence with ITGB3 in 1 paper.